FHIT (fragile histidine triad diadenosine triphosphatase)
Diseases named in the same sentence as FHIT in open-access papers (continued):
Sharing a sentence is not in itself a finding about the gene and the disease.
breast carcinoma (continued). "We then performed a similar analysis using a breast cancer dataset (Breast invasive carcinoma, TCGA PanCancer Atlas, n = 1082), the tissue of origin of the MDA-MB-231 cell line in which we observed reduced FHIT expression upon depletion of LINC00173." (PMID 38069335, 2023). "In breast cancer, multiple TSG are hypermethylated and downregulated, including for examples BRCA1, RASSF1A, p16, FHIT, and CDH1." (PMID 22110708, 2011). "In breast cancer cell lines, FHIT was deleted in 10% of the samples but not at all in primary tumors." (PMID 23805207, 2013). "This is particularly evident in breast cancer, where MACROD2 and FHIT are deleted in 28% and 15% of breast cancer cell lines, respectively, but either not at all (FHIT) or in only one out of 255 primary tumors (MACROD2)." (PMID 23805207, 2013). "In both groups, FHIT protein levels were reduced or absent in almost 70% of the breast cancer samples, whereas aberrant FHIT transcripts were detected in only 31% of the samples." (PMID 22295218, 2011). "Downmodulation or absence of FHIT protein was also evaluated in a series of 156 consecutive patients with primary breast carcinomas." (PMID 22295218, 2011). "In our experiments, we used known positive sections of corresponding tissue samples as positive controls (such as stomach tissue as the positive control for FHIT; gastric cancer as the positive control for PCNA and breast cancer as the positive control for Ki-67)." (PMID 18366613, 2008). "We found normal expression of FHIT protein in all nonproliferative lesions, but underexpression in 2% of proliferative lesions without atypia, 10% of proliferative lesions with atypia, 0% of lobular carcinoma in situ, 33% of ductal carcinoma in situ and 41% of invasive carcinomas." (PMID 17164758, 2007).
cervical carcinoma (27 papers, 1999 to 2025). A carcinoma arising from either the exocervical squamous epithelium or the endocervical glandular epithelium. "Folate deficiency and FHIT gene hypermethylation synergistically promoted HPV 16-related cervical cancerization via inflammation pathways." (PMID 41049369, 2025). "FHIT is a tumor suppressor at 3p14, which is significant copy number loss in cervical cancer, as loss of its activity results in replication stress and DNA damage." (PMID 34676167, 2021). "The FHIT gene is encoded by 10 exons in a 1.1-Kb transcript distributed over 1 Mb of genomic DNA, and aberrant FHIT transcripts were reported in cervical cancer." (PMID 28414756, 2017). "Meanwhile, correlated with clinical parameters, promoter hypermethylation and expression loss of PARK-2, RARβ, and FHIT are significantly higher in cervical cancer than in CINs and normal tissues, resulting in a significant association with tumor stage and histological grade." (PMID 29850477, 2018). "And this deletion may cause protein expression decrease, suggesting that FHIT is an important factor in the transition of CIN to cervical cancer." (PMID 28414756, 2017). "FHIT is a tissue-specific tumor suppressor gene, and its inactivity is often associated with the occurrence and development of cancer, especially epithelial cancer, including cervical carcinomas." (PMID 25880193, 2015). "Cervical cancer was the first to be assessed for Fhit protein expression by immunohistochemistry and Fhit loss or reduction was observed in ∼70% of cervical cancers, a loss that correlated with the detection of aberrant FHIT RT–PCR amplification products." (PMID 12771912, 2003). "Reduced or loss of FHIT expression has been confirmed in solid tumors like head and neck, GIT, renal cell, breast, cervical cancers and others." (PMID 38587694, 2024). "Methylated HS3ST2, CCNA1, EGFR promoter, FHIT, TFPI2, CpG6, and CpG15 sites were associated with HPV16 infection in the progression of cervical cancer." (PMID 29850477, 2018). "Both the 3p14.2 locus copy number and FHIT protein expression levels showed significant decreases when CIN transitioned to cervical cancer." (PMID 28414756, 2017). "In our study, as CIN progressed to cervical cancer, FHIT copy number and protein expression levels both showed significant differences." (PMID 28414756, 2017). "The most significant decrease was from CIN III to cancer stage I (223000.19 to 65783.97, P < 0.001), suggesting that FHIT is an important factor in the transition of CIN to cervical cancer." (PMID 28414756, 2017). "Generally, the average copy number of FHIT in cervical cancer was decreased compared to that of CIN (1.43 to 0.98, P < 0.001), but not from normal cervical samples to CIN (1.51 to 1.43, P = 0.595)." (PMID 28414756, 2017). "In this study, we used DIPS-PCR and determined that the FHIT gene locus had the highest frequency of HPV integration in cervical cancer tissues." (PMID 28414756, 2017). "Then, with fluorescence in situ hybridization (FISH), we found that the FHIT copy number was lower in cervical cancer samples compared to CIN samples." (PMID 28414756, 2017). "In the cervical cancer samples, we have demonstrated that FHIT is one of the highest frequency loci for HPV integration." (PMID 28414756, 2017). "Protein levels of FHIT were also reduced during CIN transition to cervical cancer as measured by an IHC assay." (PMID 28414756, 2017). "Wali reported that the FHIT gene loses its ability to produce its specific protein in the early stages of lung, head and neck, esophageal, colorectal, breast, and cervical cancer." (PMID 25091577, 2014). "Our recent study has demonstrated novel missense mutation in FHIT gene and interpreted the effect in HPV-mediated cervical cancer in Indian women." (PMID 23573237, 2013).
cervical carcinoma (continued). "Many studies have reported altered FHIT expression in a variety of carcinomas including head and neck, lung, kidney, gastrointestinal, and breast cancer and in 68% of cervical carcinoma cell lines." (PMID 16248899, 2005). "This is consistent with a negative correlation found between the presence of HPV E6/E7 transcripts and abnormal FHIT transcripts in cervical cancers." (PMID 11875703, 2002). "We therefore speculate that HPV integration might cause FHIT expression loss and consequently MHC-I downregulation on cervical cancer cells." (PMID 32545680, 2020). "Also, allelic losses, homozygous deletions, and aberrant FHIT transcripts are common in cervical cancers but occur at much lower frequencies in precancerous lesions." (PMID 28414756, 2017). "In addition, we assessed the potential of FHIT as a biomarker for the transition of CIN to cervical cancer." (PMID 28414756, 2017). "Also, FHIT gene inactivation in cervical cancer was found to be strongly correlated with 5'-CpG island hypermethylation have been reported in previous study." (PMID 28414756, 2017). "In addition, it is known that in cervical cancer, inactivation of the FHIT gene by 5`-CpG island methylation plays an important role in the occurrence of cervical cancer." (PMID 23067401, 2012). "However, in a study of FHIT methylation in cervical cancer, the methylation pattern identified by bisulfite genomic sequencing did not correlate with the MSP." (PMID 16928264, 2006). "Although the study involved normal and lesional DNAs from only 14 cervical cancers, the authors concluded that the ‘findings suggest essential roles of genes on these 3p loci, particularly the FHIT gene, in participating in clonal selection and early development of cervical cancer’." (PMID 12771912, 2003). "This implied FHIT may play an important role in CIN evolution to cervical cancer." (PMID 28414756, 2017). "Three genes of LRP1B, FHIT, and DLG2 belong to a group of 9 genes that have been reported to be the most frequently integrated spots for HPV in cervical carcinomas." (PMID 32905102, 2020). "The methylation rates of IFN-γ, FHIT, MGMT, CDKN2A, SALL3, and gene promoters were significantly higher in cervical cancer tissues than those in CIN and normal cervical tissues, which are related to the progression of cervical oncogenesis." (PMID 29850477, 2018). "We analyzed the copy number variation of FHIT and HPV in normal cervix, CIN and cervical cancer by FISH." (PMID 28414756, 2017). "Three very large CFS genes FHIT, LRP1B and DLG2 were the sites of HPV integrations in multiple cervical cancers and the protein expression of FHIT and LRP1B was down regulated when HPV integrated in their introns." (PMID 26262638, 2015). "We confirmed that DAPK1, RARB, SLIT2, and WIF1 are aberrantly methylated in cervical cancer compared to normal tissue, whereas, APC, CDH1 and FHIT are less commonly methylated." (PMID 25826459, 2015). "Currently, the known repressor genes are related to cervical cancer including CCNA1, CHFR, FHIT, PAX1, PTEN, SFRP4, TSLC1 and etc." (PMID 21999220, 2011). "The FHIT gene is a tumor suppressor gene located on chromosome 3p14.2 and LOH on the short arm of chromosome 3 and has been detected in up to 75% of cervical carcinomas." (PMID 16248899, 2005). "The most significant reductions of FHIT copy numbers and FHIT expression were from CIN III to cancer stage I, This finding indicated that there was obvious deletion in the FHIT gene locus when CIN progress into cervical cancer." (PMID 28414756, 2017). "Restoration of FHIT expression induced apoptosis in all FHIT-negative cell lines and SiHa cells among cervical carcinomas." (PMID 25880193, 2015). "These researches demonstrated us that FHIT and PTEN in Hela cells and FHIT and CHFR in Siha cells might have the other regulation pathways for carcinogenesis or transcription control, and which needs more tests of cervical cancer cells and clinical specimens." (PMID 21999220, 2011).
cervical carcinoma (continued). "Finally, we employed receiver operating characteristic curve (ROC curve) analysis to evaluate the potential of all these indexes in distinguishing CIN and cervical cancer, and the HPV copy number, FHIT copy number and FHIT protein expression levels have good diagnostic efficiencies." (PMID 28414756, 2017). "All of the results suggested that FHIT may be a latent target of cervical cancer treatment, but in our study, integration of HPV into the FHIT gene was only detected in 3 samples, and FHIT copy number and expression levels decreased in a large proportion of the cervical cancer samples." (PMID 28414756, 2017). "Other genes reportedly hypermethylated in cervical cancer with little to no methylation in normal or low-grade CINs include DAPK1, RARB, TIMP3, CCNA and FHIT." (PMID 25826459, 2015). "HPV16 sequences were not present in abnormal FHIT transcripts and the presence of HR HPV E6/E7 transcripts and abnormal FHIT transcripts were negatively correlated in cervical cancer." (PMID 11875703, 2002).
esophageal cancer (14 papers, 2006 to 2025). A primary or metastatic malignant neoplasm involving the esophagus. "In esophageal cancer, variations in the FHIT gene mainly arise from a loss of exon five or eight or hypermethylation of the FHIT promoter." (PMID 36831487, 2023). "Cigarette smoke primarily induces cancer by forming covalent bonds between its carcinogenic components and DNA, leading to the formation of DNA adducts that cause the mutations in crucial genes, including FHIT, that are associated with esophageal cancer." (PMID 38002698, 2023). "The positive expression rate of FHIT (61%; 45/74) in the oesophageal cancer tissues was identified to be lower than that of the adjacent healthy tissues (97%; 29/30) and the difference was statistically significant (P<0.01)." (PMID 25436004, 2015). "In addition, the BRCA2, MLH1 and FHIT genes may be involved in the genesis of oesophageal cancer in susceptible populations, and the abnormal changes in BRCA2 and MLH1 expression are important molecular events in the occurrence of oesophageal cancer in OCFH + patients." (PMID 25436004, 2015). "The hyper-methylation of the 5′ promoter region of the FHIT tumor-suppressor gene has been observed in human cell lines of leukemia, as well as in breast, pancreatic and esophageal cancer." (PMID 24396396, 2014). "While hypermethylation of FHIT gene has been described in 33% to 69.4% of ESCC cases, it is also known that deletion and loss of protein expression are frequent in esophageal carcinoma." (PMID 20163722, 2010). "In oesophageal cancer, it is known that p16, FHIT and VHL are inactivated by promoter hypermethylation." (PMID 18219292, 2008). "Four of five SA ESCC cell lines and four of ten primary tumors had a FHIT deletion suggesting that FHIT might be of relevance in SA esophageal cancer as found in other parts of the world where the incidence of this type of cancer is high." (PMID 16895604, 2006). "Previous studies have demonstrated that the overexpression of FHIT, following transfection or infection of the cells with exogenous FHIT, may significantly inhibit cell growth and induce apoptosis in leukemia, as well as breast and esophageal cancer cell lines." (PMID 24396396, 2014). "For example, introduction of the FHIT gene into several esophageal cancer cell lines lacking FHIT induced Caspase-dependent apoptosis and cell cycle arrest." (PMID 38069335, 2023). "The positive expression rates of FHIT (61%; 45/74), BRCA2 (50%; 37/74) and MLH1 (27%; 9/33) in the oesophageal cancer tissues were significantly lower than those in the healthy tissues adjacent to the cancer (97% [29/30], 87% [26/30] and 73% [25/41], respectively)." (PMID 25436004, 2015). "The synergistic effect of FHIT, BRCA2, MLH1 and other relevant factors may be the molecular bases for the genesis of oesophageal cancer." (PMID 25436004, 2015). "In addition, the synergistic effects of FHIT, BRCA2, MLH1, and other related factors may be the molecular basis of esophageal cancer." (PMID 40539057, 2025). "Another study involving Adenoviral- fragile histidine triad (Ad-FHIT) treatment of esophageal cancer cells found overexpression of ST3GAL6 in apoptotic cells compared with non-apoptotic cells, suggesting Ad-FHIT treatment’s role in the inhibition of a sialyltransferase-associated metastasis." (PMID 36547200, 2022).
gastric cancer (14 papers, 2003 to 2023). A primary or metastatic malignant neoplasm involving the stomach. "The fragile histidine triad (FHIT) is also linked to protecting against developing H. pylori-related gastric cancer." (PMID 36678166, 2023). "A positive association between FHIT expression and favorable overall survival was found in patients with gastric cancer (p < 0.05)." (PMID 29296239, 2017). "In contrast, our bioinformatics data indicated that FHIT mRNA expression was negatively associated with overall and progression-free survival rates of the patient with gastric cancer, even stratified by clinicopathological features." (PMID 29296239, 2017). "Our meta-analysis showed that FHIT expression was positively linked to the favorable prognosis of the patients with gastric cancer." (PMID 29296239, 2017). "The pooled result from 7 datasets demonstrated a positive association between FHIT expression and favorable overall survival in the patients with gastric cancer (HR = 1.53, 95% CI: 1.30–1.80, p < 0.0001)." (PMID 29296239, 2017). "Loss of FHIT protein expression correlates with disease progression and poor differentiation in gastric cancer." (PMID 26360582, 2015). "A somatic missense mutation (exon 6, codon 61, ACG → ATG) of FHIT has also been identified in gastric cancers." (PMID 26360582, 2015). "It was reported that alterations in the FHIT locus detected by DNA and/or RT–PCR analysis closely correlated with a loss of Fhit protein expression in lung and gastric carcinomas." (PMID 14760383, 2004). "Taken together, we concluded that FHIT loss might be employed as a potential biomarker for aggressiveness of gastric cancer." (PMID 29296239, 2017). "A total of 21 articles on the relationship between FHIT expression and cancer risk, clinicopathological or prognostic parameters of gastric cancer were retrieved for our meta-analysis by immunohistochemistry from PubMed, Web of Science, BIOSIS, SciFinder and CNKI." (PMID 29296239, 2017). "CRCs and gastric carcinomas with MMR deficiency frequently also carry large deletions in FHIT." (PMID 29069730, 2017). "Loss of FHIT expression has been found in the gastric mucosa of patients with gastric carcinoma." (PMID 25875960, 2015). "In summary, FHIT and IL-8 may constitute targets of the genetic susceptibility to gastric cancer in patients with family histories of gastric cancer, especially first-degree relatives of gastric cancer." (PMID 25875960, 2015). "Therefore, the FHIT gene may be one of the targets of the genetic susceptibility to gastric cancer in patients with family histories of gastric cancer, especially first-degree relatives of gastric cancer." (PMID 25875960, 2015). "It has been reported that FHIT expression potentiates doxorubicin cytotoxicity in the bladder carcinoma tissue and gastric cancer cell line." (PMID 31089360, 2019). "As a result, we found down-regulated FHIT expression in gastric cancer, compared with normal mucosa (p < 0.00001)." (PMID 29296239, 2017). "There appeared the comparison between FHIT expression and clinicopathological characteristics of gastric cancer in 19 pieces of paper, including sex, depth of invasion, lymph node metastasis, distant metastasis, TNM staging and Lauren's classification." (PMID 29296239, 2017). "The down-regulated FHIT expression was found in gastric cancer, compared with normal mucosa and dysplasia (p < 0.05)." (PMID 29296239, 2017). "FHIT expression was negatively related to lymph node metastasis (p < 0.00001) and distant metastasis (p = 0.0002) of gastric cancer." (PMID 29296239, 2017). "In the present study, we performed a meta- and bioinformatics analysis to clarify the clinicopathological and prognostic significances of FHIT expression in gastric cancer at both mRNA and protein levels." (PMID 29296239, 2017). "A higher FHIT expression was detected in T0-1 than T2-4 gastric cancer (p < 0.00001) or T0-2 than T3-4 ones (p = 0.009)." (PMID 29296239, 2017).